SMURF2 (SMAD specific E3 ubiquitin protein ligase 2)
Diseases named in the same sentence as SMURF2 in open-access papers (continued):
Sharing a sentence is not in itself a finding about the gene and the disease.
tumor (80 papers, 2003 to 2026). "Smurf2-deficient mice are prone to various cancers, suggesting its potential role as a tumor suppressor due to altered histone modification and chromatin compaction." (PMID 38993132, 2024). "Therapies that inhibit HIF1α directly or modulate its associated regulatory mechanisms, such as the SMURF2 pathway, have the potential to impair tumor angiogenesis, reduce immune suppression, and reprogram tumor metabolism." (PMID 39697237, 2024). "Our work advances the understanding of the function of Smurf1 and Smurf2 in tumor biology and provides new potential diagnostic and drug targets for Shh-MB." (PMID 37537194, 2023). "The tumor-suppressive role of Smurf2 was found to be associated with cell migration and EpCAM expression; hence, Smurf2 can be considered a positive biomarker of cancer stem cell-like properties." (PMID 35361871, 2022). "A low level of Smurf2 expression is significantly associated with unfavorable clinical features, such as tumor thrombus (P = 0.045), and indicated a poor prognosis of HCC patients." (PMID 35509688, 2022). "The low expression of Smurf2 in HCC was significantly associated with macrovascular or microvascular tumor thrombus and the impairment of overall survival and disease-free survival." (PMID 35509688, 2022). "The tumor-suppressive role of Smurf2 was found to be associated with cell migration and EpCAM expression, which is associated with stem cell-like properties of cancer cells." (PMID 35361871, 2022). "We have also reported that loss of EGFR protein upon knock-down of the E3 ligase SMURF2, induced autophagy and sensitized tumor cells." (PMID 27612423, 2016). "Additionally, the tumor-suppressive role of Smurf2 was reported to be associated with the degradation of YY1 and downregulation of SENP1/c-myc15." (PMID 35361871, 2022). "Interestingly, Smurf2 has been implicated in seemingly contradictory roles as a pro-oncogenic factor and as a tumor suppressor." (PMID 35710591, 2022). "Cox regression model for OS showed that macrovascular or microvascular tumor thrombus and tumor differentiation were significantly associated with an increased risk of cancer-related death, while Smurf2 expression was significantly associated with decreased risk of cancer-related death." (PMID 35509688, 2022). "Smurf2 expression was significantly associated with grade of the tumor (P < 0.001)." (PMID 29534682, 2018). "This association suggests that targeting progerin through the Smurf2-mediated autophagy might be a promising direction to eradicate tumor cells, though more research is needed in this regard." (PMID 30116722, 2018). "All Smurf2-deficient mice develop visible DLBCL tumor starting at 15 months of age." (PMID 28107482, 2017). "For young Smurf2 deficient mice compared with wild type mice, there was a clear predicted risk of cancer promotion due to the miRNA signature detection 15 months prior to tumor formation." (PMID 28107482, 2017). "Since the epigenetic alterations also occur in the spleen and primary dermal fibroblasts freshly isolated from Smurf2-deficient mice, loss of Smurf2 likely initiates a cascade of events early on in the life of affected mice that culminate in the tumor formation as they age." (PMID 22429979, 2012). "Furthermore, the Smurf2-Smad3-RANKL axis described in the previous section could also potentially be involved in tumor formation in Smurf2-deficient animals." (PMID 30116722, 2018). "Immunohistochemistry staining of tumor sections also supported the finding that CASC3 expression was downregulated in tumors with Smurf2 overexpression." (PMID 40978141, 2025).
tumor (continued). "The findings from the TCGA-OSCC dataset and analysis conducted on TNMplot.com revealed that the mRNA expression level of SMURF2 was significantly higher in the tumor group in comparison to the normal group (p < 0.001 or p < 0.01)." (PMID 38698292, 2025). "Collectively, these results suggest that Smurf2 suppresses tumor growth in vivo, potentially by downregulating CASC3." (PMID 40978141, 2025). "Strikingly, the downregulation of Smurf2 promotes cell viability through CASC3, while overexpression of Smurf2 retards tumor growth in mouse models." (PMID 40978141, 2025). "Tumor volume data further confirmed that overexpression of Smurf2 led to reduced tumor size in mice." (PMID 40978141, 2025). "The comparative analysis of SMURF2 gene expression across various cancer types indicated differential expression patterns between normal and tumor tissues." (PMID 38698292, 2025). "The dysregulated expression of Smurf2 has been reported across a wide spectrum of human tumours, such as colorectal carcinoma, pancreatic cancer, lung cancer and hepatocellular carcinomas." (PMID 39871432, 2025). "Western blotting analysis of tumor tissues showed that overexpression of Smurf2 reduced CASC3 expression." (PMID 40978141, 2025). "Recent studies have shown that Smurf2 plays a dual role in human cancers, depending on protein interactions, tumour type, and other unclear factors." (PMID 39871432, 2025). "SMURF2, an E3 ubiquitin ligase, mediates the ubiquitination and degradation of several cancer-related proteins, modulating signaling pathways that affect tumor growth, migration, and metastasis." (PMID 39697237, 2024). "Examining the roles of SMURF2 and HIF1α in different cancers reveals their complex contributions to tumor progression and potential as therapeutic targets." (PMID 39697237, 2024). "Targeting the SMURF2-HIF1α pathway poses significant safety challenges due to SMURF2’s dual role as both a tumor suppressor and oncogene, depending on context." (PMID 39697237, 2024). "SMURF2: A Dual Role in Protein Degradation and Tumor Suppression: Under normoxic conditions, SMURF2 utilizes its E3 ubiquitin ligase activity to ubiquitinate and degrade HIF1α, maintaining low intracellular protein levels." (PMID 39697237, 2024). "Recent studies have demonstrated that SMURF2 mediates the ubiquitination and subsequent degradation of HIF1α, thereby modulating the cellular response to hypoxia—a key driver of tumor progression and metastasis." (PMID 39697237, 2024). "This function shifts under hypoxic tumor conditions, where SMURF2 is crucial for the polyubiquitination and proteasomal degradation of HIF1α." (PMID 39697237, 2024). "SMURF2’s role as both a tumor suppressor and an oncogene highlight its complexity and potential as a context-dependent target, while its regulation of HIF1α provides new insights into controlling hypoxia-driven cancer progression." (PMID 39697237, 2024). "SMURF2’s role in cancer is context-dependent, acting both as a tumor suppressor and, paradoxically, as an oncogene in certain cancers." (PMID 39697237, 2024). "While SMURF2 is recognized as a tumor suppressor, its expression in cancer cells varies depending on the type and stage of cancer." (PMID 39697237, 2024). "Beyond its role in HIF1α regulation, SMURF2 exerts extensive control over cellular processes central to tumor progression, including chromatin remodeling, DNA damage repair, ferroptosis, and cellular stress responses." (PMID 39697237, 2024). "We discuss SMURF2’s dual functionality as both a tumor suppressor and, in certain contexts, an oncogenic factor, underscoring its potential as a highly versatile therapeutic target." (PMID 39697237, 2024). "Smurf2 has been reported to play a dual role in cancers by functioning as both tumor promoter and suppressor by regulating the stability of proteins in tumorigenesis." (PMID 38993132, 2024).
tumor (continued). "This modulation impacts tumor progression, angiogenesis, metabolic reprogramming, and cell survival, establishing SMURF2 as a potent therapeutic target." (PMID 39697237, 2024). "Specifically, SMURF2’s activity facilitates the maintenance of low intracellular HIF1α levels, impacting cellular responses to hypoxia and inhibiting tumor growth and metastasis." (PMID 39697237, 2024). "SMURF2, an E3 ubiquitin ligase, plays a crucial role in HIF1α degradation, limiting HIF1α’s ability to promote tumor adaptation to hypoxic environments." (PMID 39697237, 2024). "TME and Therapeutic Challenges: The TME significantly influences the SMURF2-HIF1α pathway, primarily through HIF1α, creating a critical feedback loop essential for tumor adaptation and survival." (PMID 39697237, 2024). "This activity ensures proper chromosomal segregation during cell division, preventing aneuploidy and genomic instability, hallmarks of cancer cells, thereby reinforcing SMURF2’s function as a tumor suppressor." (PMID 39697237, 2024). "The elucidation of SMURF2’s role in HIF1α regulation opens potential strategies for cancer therapy, particularly in hypoxia-driven tumors where HIF1α plays a key role in tumor aggressiveness, metastasis, and resistance to therapy." (PMID 39697237, 2024). "Their findings underscore the potential of targeting HIF1α pathways, including through SMURF2 modulation, to impede tumor progression." (PMID 39697237, 2024). "In a murine Smurf2-deficient model of spontaneous DLBCL initiation, the presence of distinct miRNAs in the serum, long before actual tumor formation, was identified, the majority of which were also found enriched in PDTX DLBCL models." (PMID 39337470, 2024). "Recent insights have highlighted the critical role of SMURF2 in the process of ubiquitination and degradation of HIF1α under both normoxic and hypoxic conditions, a process critical for modulating tumor progression, angiogenesis, and cellular metabolism." (PMID 39697237, 2024). "Intriguingly, within the context of cancer, these proteins appear to have unique roles as either tumor suppressors or oncogenes, with Smurf2 possibly behaving as both depending on context." (PMID 38147466, 2024). "By targeting negative regulators for degradation, SMURF2 enhances β-catenin activity, which can drive tumor progression, particularly in cancers where Wnt signaling is aberrantly active." (PMID 39697237, 2024). "This role of SMURF2 as a tumor suppressor aligns with its involvement in cellular senescence and stability of tumor-suppressing pathways." (PMID 39697237, 2024). "SMURF2, a tumor suppressor, regulates various cellular processes beyond degrading HIF1α, including the ubiquitin-proteasome system’s stability, essential for normal cell function." (PMID 39697237, 2024). "Cell proliferation-related genes suggested a possible tumor-suppressing role for SMURF2, whereas the detailed function of this ubiquitin ligase remained unclear." (PMID 37497010, 2023). "Yu et al22 also reported that USP47 and SMURF2 can mediate CC cell proliferation and tumor progression by reversibly manipulating SATB1 ubiquitination." (PMID 37158531, 2023). "We also examined pHSP25 and Smurf2 in tumor tissues and observed an inverse correlation between them, similar to that observed in fibrotic lungs." (PMID 36611161, 2023). "Tumors derived from MIR503HG-depleted FePD or MAC-1 cells were smaller in size and demonstrated a remarkable increase in the levels of SMURF2, whereas the levels of TGFβ receptor were noticed to be suppressed in the tumor tissues." (PMID 37568787, 2023). "SMURF2 expression was reduced in the tumor tissues of patients with NSCLC and high SMURF2 expression was significantly correlated with favorable outcomes." (PMID 37497010, 2023). "The effects of SMURF2 on tumorigenesis were evaluated in vivo using tumor-bearing assays in nude mice." (PMID 37497010, 2023).
tumor (continued). "The autophagy-mediated tumor suppressor role of SMURF2 is supported by findings that show SMURF2 can bind and ubiquitylate Lamin A and its disease-correlated mutant variant Progerin." (PMID 36918822, 2023). "Here, we reported a tumor-suppressive role for Smurf1 and Smurf2 during Shh-MB progression, which was proven by the following evidence." (PMID 37537194, 2023). "SMAD-specific E3 ubiquitin protein ligase 2 (SMURF2) functions as either a tumor promoter or tumor suppressor in several tumors." (PMID 37497010, 2023). "The upregulation of SMURF2 predicted a favorable prognosis of patients with CRC and liver metastases, and the tumor-suppressive role of SMURF2 was found to be associated with cell migration and EpCAM expression." (PMID 36831013, 2023). "In recent years, the biological roles of SMURF2 have been identified in different tumors, including tumor metastasis, apoptosis, cell cycle progression, senescence, and genomic stability." (PMID 37497010, 2023). "In conclusion, our findings suggest that SMURF2 prevents tumor progression by regulating the cell cycle in NSCLC cells." (PMID 37497010, 2023). "Collectively, these data suggest that Smurf1 and Smurf2 play an important role in driving Shh signaling-mediated tumor growth, possibly through the ubiquitin E3 ligase activity." (PMID 37537194, 2023). "It has been reported that Smurf2 appears to act as an oncogene, promoting tumor development through stabilization of KRAS and EGFR." (PMID 36611161, 2023). "A higher level of Smurf2 expression was found in adjacent non-tumor liver tissues, whereas HCC tissues and HCC cell lines." (PMID 35509688, 2022). "The ability of Smurf2 to ubiquitinate and degrade RNF20, a RING-family E3 that controls histone H2B ubiquitination and genome stability, has been implicated in the tumor suppressive role of Smurf2 in a wide spectrum of tumors." (PMID 36612252, 2022). "In this study, we found that Smurf2 participates in a common mechanism for tumor resistance to cisplatin and radiation." (PMID 35710591, 2022). "For example, the expression of Smurf2 increased in esophageal squamous cell carcinoma and pancreatic carcinoma, which was related to tumor invasion and lymph node metastasis." (PMID 35509688, 2022). "The results showed that in contrast to tumor cells SMURF2 knockdown in IMR-90 and BJ1 cells markedly increased KAP1 protein levels, suggesting that, in these cells, SMURF2 operates as a negative regulator of KAP1 expression." (PMID 35406379, 2022). "The expression of Smurf2 is closely related to the occurrence, development, and metastasis of the tumor." (PMID 35509688, 2022). "Smurf2 is thought to act as a tumor promoter or suppressor by regulating some proteins involved in tumorigenesis under different conditions." (PMID 35509688, 2022). "The current results confirmed that the low expression of Smurf2 was closely related to the formation of tumor thrombus (P = 0.045)." (PMID 35509688, 2022). "The comparison of the relative expression of Smurf2 expression between tumor tissue and adjacent tissue indicated that Smurf2 was downregulated in HCC tumor tissue compared with adjacent tissue." (PMID 35509688, 2022). "Some studies have explored the tumor-suppressive role of Smurf2 and the corresponding mechanisms in the progression of CRC using a cell line and/or an animal model." (PMID 35361871, 2022). "Significantly enhanced upregulation of Smurf2 protein expression was found in post-chemoRT lung tumor samples compared to pre-chemoRT tumor samples." (PMID 35710591, 2022). "Smurf2 was downregulated in HCC tissues compared to that of corresponding non-tumor liver specimens." (PMID 35509688, 2022). "The expression of Smurf2 was significantly correlated with macrovascular or microvascular tumor thrombus (P = 0.045)." (PMID 35509688, 2022). "The human HCC tissues presented a low expression of Smurf2 as compared to that of adjacent non-tumor liver tissues." (PMID 35509688, 2022).
tumor (continued). "It has been reported that Smurf2 plays a dual role in cancer as both tumor promoter and suppressor by regulating the protein stability in the process of tumorigenesis and development." (PMID 35509688, 2022). "In esophageal squamous cell carcinoma, increased expression levels of SMURF2 correlated with tumor development and a poor prognosis." (PMID 33418880, 2021). "Smurf2 acts as a ubiquitin ligase for Smad, and its expression is higher in tumor cells, mainly at the tumor front, where the proliferation in esophageal squamous cell carcinoma is higher." (PMID 34769401, 2021). "Unlike TRAF6, TRAF4 causes ubiquitination-mediated degradation of SMURF2 and SMURF1, which leads to malignancy in certain tumor types." (PMID 33418880, 2021). "Similar events are apparent in breast and prostate cancers also, suggesting that the repression of TGFβ signaling by SMURF2 occurs during tumor progression." (PMID 33418880, 2021). "In neoplastic diseases, SMURF2 was shown to exert both tumour-promoting and suppressor activities, depending on tumour type, stage, molecular and cellular contexts, and other still unidentified factors." (PMID 33430646, 2021). "We previously demonstrated that the E3 ubiquitin ligase SMURF2 plays a critical tumor suppressing role via its interaction with RNF20 (ring finger protein 20) in shaping chromatin landscape and preserving genomic stability." (PMID 33097595, 2020). "The profound impact of SMURF2 on the chromosomal landscape accounts for its important role as a tumor suppressor through maintaining genomic stability." (PMID 33097595, 2020). "Among many signal cascades, TGF-β signaling is one link between Smurf2 and tumor cellular responses." (PMID 33718111, 2020). "SMURF2, an E3 ubiquitin ligase and suggested tumor suppressor, operates in normal cells to prevent genomic instability and carcinogenesis." (PMID 31003445, 2019). "All these efforts are needed to determine why and how SMURF2 loses its tumor suppressor functions and transforms to oncoprotein." (PMID 31003445, 2019). "SMURF2 has been reported to have a dual role in cancer, acting as both a tumor promoter and a tumor suppressor." (PMID 31581360, 2019). "SMURF2 plays an important role in various physiological and pathological contexts: development, proliferation/apoptosis, senescence, tumorigenesis/tumor suppression, and metastasis." (PMID 30696809, 2019). "Both protein levels and mRNA levels of SMURF2 were reduced in miR‐195 and miR‐497 overexpressed tumor tissues compared with the control." (PMID 31581360, 2019). "Our studies also uncovered that Smurf2 is a determinant of Topo IIα protein levels in cancer cells and tissues, and is a factor affecting tumor cell sensitivity to the Topo II-targeting drug, etoposide." (PMID 30116722, 2018). "Altogether, these findings establish Smurf2 as a potent tumor suppressor, preventing the transformation of normal cells into cancerous ones." (PMID 30116722, 2018). "The currently available data stipulate that Smurf1 acts as an oncogene, whereas Smurf2 operates both as a tumor suppressor and a tumor promoting molecule, depending on the tumor stage, type, molecular binding partners, and other still unidentified factors." (PMID 30116722, 2018). "The percentage of samples with differential Smurf2–lamin A/C scores in cancer TMAs ranged between approximately 40% and 80%, dependent on the tumor type." (PMID 29405587, 2018). "Under the described experimental setting, Smurf2 appears to act as an oncogene, promoting tumor development." (PMID 30116722, 2018). "Evidence points to Smurf2 as a potent tumor suppressor operating in normal cells to prevent cell transformation and carcinogenesis." (PMID 30116722, 2018).